BCL2 (BCL2 apoptosis regulator)
Diseases named in the same sentence as BCL2 in open-access papers (continued):
Sharing a sentence is not in itself a finding about the gene and the disease.
Stroke (continued). "These key circRNAs were associated with a large range of key functional genes involved in ischemic injury, such as HIF-1, Bcl-2, and MMP-9, in response to stroke through the adsorption of miRNAs and the regulation of target genes." (PMID 34868302, 2021). "With the treatment of DSCXQ, the downregulation of Bax, Cleaved Caspase-3, and up-regulated of Bcl-2, was achieved, implicating the neuroprotective effects of DSCXQ against neuronal apoptosis on a stroke model." (PMID 34026822, 2021). "Such neuronal death in a caspase-independent manner was described in stroke, in which NG2 glia produce Bcl-2/E1B-19K-interacting protein 3 (BNIP3), a proapoptotic member of the Bcl-2 family proteins." (PMID 32265656, 2020). "We showed in our experiment that the ratio of Bcl2 to PUMA increased in response to G-CSF in the Frontal and Middle brain regions in the BCAO stroke model." (PMID 31907023, 2020). "Expression of SCG2 is modulated by extracellular calcium, and it can induce expression of the anti-apoptotic protein Bcl2 through activation of JAK2/STAT3 signaling, providing protection in a murine stroke model." (PMID 30670947, 2018). "Similarly to our studies, simultaneous increase in anti-apoptotic BCL2 and pro-apoptotic BAX was observed during prenatal exposure to cocaine and cellular models of stroke and Alzheimer’s disease." (PMID 39771121, 2024). "Experimental stroke studies which incorporate social isolation or social defeat stress have shown that both tissue and functional stroke outcome is affected by the increased expression of TNF-α and IL-6, increased glucocorticoid production, and suppression of the protooncogene bcl-2." (PMID 32477259, 2020). "Administering simplex virus (HSV) vector expressing Bcl-2 led to neuroprotection via Bcl-2 overexpression when it was given 1.5 h after stroke but not 5 h after stroke." (PMID 29896438, 2018). "In order to determine the Danhong injection plus t-PA prolonged the thrombolytic window to 4.5 h for treatment of focal embolic stroke in rats, real time RT-PCR was performed to determine the relative levels of BAX, Bcl-2, and caspase-3 mRNA transcriptions in rat tissue." (PMID 29681849, 2018). "BCL-2, which is a downstream target of CREB, has previously been shown to be beneficial in stroke." (PMID 25331941, 2014). "In contrast, Bcl-2 immunoreactivity in the same striatal area of high dose minocycline-treated stroke animals was not significantly differrent from vehicle-treated stroke animals (100 mg/kg: 1.14 ± 0.22 density/0.05 mm2)." (PMID 19807907, 2009).
mantle cell lymphoma (76 papers, 2010 to 2025). Mantle cell lymphoma is a rare form of malignant non-Hodgkin lymphoma affecting B lymphocytes in the lymph nodes in a region called the ``mantle zone''. "Targeting BCL-2 through venetoclax is an effective therapy for a series of hematological cancers, such as mantle cell lymphoma (MCL), but resistance to venetoclax is an increasing challenge that needs to be overcome." (PMID 36672458, 2023). "In mantle cell lymphoma synergistic activity of BET antagonists combined with a Bcl-2 inhibitor has been demonstrated in cells resistant to ibrutinib." (PMID 33298182, 2020). "Bcl‐2 and Mcl‐1 are antiapoptotic proteins that are also commonly overexpressed in mantle cell lymphoma." (PMID 30065968, 2018). "We then used these lipidoid nanoparticles to examine the effect of silencing a trio of genes—Cyclin D1, Bcl‐2, and Mcl‐1—on mantle cell lymphoma apoptosis and proliferation rates." (PMID 30065968, 2018). "Bcl-2 and cyclin D1 translocations found respectively in follicular lymphomas (FL) and mantle cell lymphomas (MCL), occur during V(D)J recombination." (PMID 27729620, 2017). "BCL2 gain/amplification are commonly associated with the DLBCL activated B-cell-like (ABC) subtype and mantle cell lymphoma (MCL), two aggressive types of NHL." (PMID 24788952, 2014). "Therefore, the use of ASO against Bcl-2 (oblimersen) can also indirectly inhibit the transcription of CCND1a through the interaction between Bcl-2 and CCND1a, resulting in higher proliferation and invasive of mantle cell lymphoma." (PMID 37024471, 2023). "A 2021 study found that Tucidinostat induces apoptosis in DLBCL cells by targeting the HDACs/STAT3/Bcl-2 pathway, while Abexinostat has proven effective in relapsed or refractory follicular lymphoma (FL) and mantle cell lymphoma (MCL)." (PMID 40299416, 2025). "At pre-clinical level, PRT543 has shown that when used in combination with venetoclax (a BCL-2 inhibitor), it sensitised a mouse model of ibrutinib-resistant mantle cell lymphoma (MCL)." (PMID 39703687, 2024). "Venetoclax, a BCL-2 inhibitor, has proven to be effective in several hematological malignancies, including mantle cell lymphoma (MCL)." (PMID 36672458, 2023). "Moreover, a related study found that Bcl-2 silencing was associated with decreased CCND1a expression but not with CCND1b in mantle cell lymphoma cell lines in vitro." (PMID 37024471, 2023). "Low FBXO10 mRNA resulting in high BCL2 also appears to drive accumulation of mantle cell lymphomas (MCL) derived from marginal zone or memory B cells." (PMID 33914737, 2021). "Venetoclax is an anti-BCL2 agent approved in Europe for the treatment of chronic lymphocytic leukemia (CLL) that has shown therapeutic activity in mantle cell lymphoma (MCL) and other hematological malignancies." (PMID 34938664, 2021). "Early clinical data as well as preclinical data indicate that also in mantle cell lymphoma, which is largely characterized by high expression of BCL-2 and showed a more promising clinical response to venetoclax than other subtypes of B-cell lymphoma, MCL-1 may be a valuable therapeutic target." (PMID 33308268, 2020). "For example, no previous study has systematically described the incidence and evaluated the prognostic role of a double hit with MYC and BCL2 rearrangements in mantle cell lymphoma (MCL)." (PMID 26517511, 2015). "In another hematological neoplasm, mantle cell lymphoma (MCL), casein kinase 2 (CK2) has been shown to be over-expressed, and targeting CK2 reduces MCL-1 levels, which in turn sensitizes MCL cells to BCL-2-specific venetoclax inhibitor and presents a novel therapeutic strategy for MCL patients." (PMID 38256213, 2024). "The introduction of proapoptotic pharmacological agents such as the antiapoptotic protein Bcl-2 inhibitor VEN has revolutionized the treatment of chronic lymphocytic leukemia (CLL) and mantle cell lymphoma (MCL)." (PMID 37166997, 2023).
mantle cell lymphoma (continued). "ABT‐199, a selective targeting inhibitor of BCL‐2, has emerged as a promising treatment strategy for some B‐cell malignancies such as CLL and MCL (mantle cell lymphoma)." (PMID 36053810, 2022). "In this context, thereis a drug that targets BCL-2 in BCL-2-dependenthaematologic malignancies, such as chronic lymphoid leukaemia and mantle cell lymphoma." (PMID 34837676, 2021). "In mantle cell lymphoma (MCL), BCL-2 protein is overexpressed in virtually all cases." (PMID 32290241, 2020). "BCL-2 is aberrantly expressed in CLL, FL, mantle cell lymphoma (MCL), Waldenstrom macroglobulinemia (WM), and one-third of DLBCL22." (PMID 33139702, 2020). "High levels of BCL-2 are observed in patients with FL, CLL, mantle-cell lymphoma (MCL), and Waldenström’s macroglobulinemia." (PMID 29747654, 2018). "Venetoclax resistance mechanisms are not limited to alterations only in BCL2, as acquired mutations in pro-apoptotic BAX have been identified in mantle cell lymphoma, CLL, and AML, but none of our acquired venetoclax-resistant DLBCL lines generated a BAX mutation." (PMID 38893249, 2024). "Venetoclax, the first FDA-approved specific inhibitor of BCL-2, is highly efficient at treating CLL and mantle cell lymphoma (MCL) when used as monotherapy and has been included as the frontline CLL therapy." (PMID 37894324, 2023). "ARV‐771 significantly suppressed tumor growth in vivo and improved the survival of mantle cell lymphoma (MCL)-cell-engrafted nude mice, and co-treatment with ARV-771 and ibrutinib or venetoclax (BCL2‐antagonists) or palbociclib (CDK4/6 inhibitor) synergistically induced apoptosis in MCL cells." (PMID 38389844, 2024). "Combined MEK/Bcl‐2 inhibition was effective in MM cell lines as well, but not in mantle cell lymphoma (MCL)." (PMID 34861096, 2022). "In addition, mantle cell lymphoma expresses cyclin D1 and BCL2 but negative for CD10." (PMID 25002984, 2014).
small cell lung carcinoma (75 papers, 1998 to 2025). Small cell lung cancer (SCLC) is a highly aggressive malignant neoplasm, accounting for 10-15% of lung cancer cases, characterized byrapid growth, and early metastasis. "Further, BCL-2 upregulation mediated by lncRNA HOTTIP (HOXA distal transcript antisense RNA) was found to underlie chemoresistance in small cell lung cancer (SCLC)." (PMID 29570632, 2018). "Since small cell lung cancer appears to be the most susceptible to BCL2-inhibitors and some single-agent activity was observed in cell lines, most clinical trials with BCL2-inhibitors have concentrated on small cell lung cancer." (PMID 26556430, 2014). "Expression of Bcl-2 is life-sustaining for small-cell lung cancer cells and associated with drug resistance." (PMID 9792147, 1998). "An impactful synergistic effect was shown in the treatment of small cell lung cancer (SCLC) using the BET inhibitor ABBV-075 in combination with BCL2 inhibitors." (PMID 39838405, 2025). "The BCL2 gene contributes to the resistance of small cell lung cancer (SCLC) to Aurora kinase B (AURKB) inhibitors." (PMID 41378310, 2025). "Amongst these, the ASO targeting codon 141–147 of Bcl-2 mRNA proved most cytotoxic in a human small cell lung cancer (SCLC) cell line, SW2." (PMID 35056993, 2022). "It was reported that miR-181b-5p inhibited chemoresistance in cisplatin-resistant H446 small-cell lung cancer cells by targeting Bcl-2." (PMID 33327962, 2020). "Research was performed using Bcl-2 as a target for overcoming chemoresistance through BCL2 gene silencing to improve the clinical outcome in small-cell lung cancer." (PMID 32260280, 2020). "Suppression of Bcl-2 has been shown to inhibit tumor growth in several mouse xenograft models including H146 and H1963 (small cell lung cancer), and SKOV3; increase sensitivity to anticancer drugs; and enhance survival." (PMID 30801019, 2019). "Bcl-2 is upregulated in chemoresistant cells from small cell lung cancer, prostate cancer, ovarian and breast cancer." (PMID 35582564, 2019). "The critical regulator of apoptosis, Bcl‐2 (target of navitoclax), is overexpressed in the majority of small cell lung cancer (SCLC) tumours." (PMID 31746100, 2019). "The treatment of etoposide induces apoptosis, which is accompanied by the down-regulation of Bcl-2 expression, in small cell lung cancer (SCLC) and NSCLC cell lines." (PMID 30857233, 2019). "One recent study in small cell lung cancer also demonstrated that osteopontin increased chemoresistance to cisplatin in SBC-3 cells by suppressing bcl-2 protein downregulation." (PMID 29854808, 2018). "Small cell lung cancer (SCLC) cells grown as xenografts that have developed resistance to ABT-737 show a reduction in BIM:BCL-2 complexes compared to sensitive cells." (PMID 22898329, 2012). "The data on Bcl-2 expression in small cell lung cancer were insufficient to assess its prognostic value." (PMID 12838300, 2003). "Our data suggest the use of oligodeoxynucleotide 2009 in combination with chemotherapy for the treatment of small-cell lung cancer that overexpresses Bcl-2." (PMID 9792147, 1998). "The Bcl-2 and Bcl-XL inhibitor S44563 could significantly enhance the sensitivity of small-cell lung cancer cells to radiation." (PMID 34484337, 2021). "We hypothesize that ROR1-targeted therapy is effective in small cell lung cancer and synergizes with therapeutic BCL2 inhibition." (PMID 34088900, 2021). "It has been reported that Venetoclax could interrupt the interaction between BCL2 and the BIM complex, thereby destabilizing the BIM protein and activating PARP cleavage in a BCL2 expressing the small-cell lung cancer cell line." (PMID 32650615, 2020). "The HDAC inhibitor FR901228 could downregulate the expression of Bcl-2 and Bcl-XL, and activate caspase-9 and caspase-3 in small cell lung cancer cell lines." (PMID 26075388, 2015).
small cell lung carcinoma (continued). "However, overexpression and addiction to BCL2 has been reported in small cell lung cancer and therefore a stratified clinical trial investigating ABT-199 in patients with high BCL2-expression may be justified." (PMID 26556430, 2014). "In consistence with our study, Loriot and colleagues developed a novel BCL-2 and BCL2L1 inhibitor S44563 and found that it showed radiosensitization in small-cell lung cancer." (PMID 38316463, 2024). "Navitoclax targets BCL-2 and BCL-XL and has been widely examined in combination with other therapies in numerous solid tumors, including rhabdomyosarcoma, small cell lung cancer, and endometrial carcinoma, and in hematologic malignancies including AML and ALL." (PMID 39199601, 2024). "Overexpression of Bcl-2 is common in small cell lung cancer (SCLC), and Dol-10 has the ability of inducing Bcl-2 phosphorylation to induce apoptosis in SCLC cell lines and xenografts." (PMID 34202685, 2021). "Recent studies support this idea by showing, for example, that combination of radiotherapy with pan-Bcl-2 inhibitors ABT-737 and ABT-263 can kill breast and small cell lung cancer cells in vitro." (PMID 32630560, 2020). "For example, the Bcl-2 antagonist ABT-263 induced mitochondria-dependent apoptosis, enhancing activity of chemotherapeutic agents to inhibit small cell lung carcinoma and lymphoid malignancies in vitro and in vivo." (PMID 35582564, 2019). "Using small cell lung cancer (SCLC) as a model, we demonstrated the presence of differential addiction of cancer cells to anti-apoptotic BCL-2, BCL-XL or MCL-1, which correlated with the respective protein expression ratio." (PMID 28714472, 2017). "In adriamycin-resistant H69AR human small cell lung cancer cells infected with BCL-2 interfering RNA, the level of BCL-2 decreased and also these cells were more sensitive to daunomycin than that of the parental cells." (PMID 27391608, 2016). "A Bcl-2 mimetic, ABT-737, potentiates anticancer treatments in small cell lung cancer xenograft models." (PMID 24688727, 2013). "ABT-737, the first authentic BH3 mimetic, was developed to selectively inhibit BCL-2, BCL-XL and BCL-W, and showed promising activity against lymphoma and small-cell lung carcinoma mouse xenograft models, providing proof of principle for this therapeutic approach." (PMID 35008216, 2021). "Small molecule Bcl-2 inhibitors (ABT-737, ABT-263, and ABT-199 [Venetoclax]) were proposed to combat inherent tumor cell resistance to ITs by studies in cervical adenocarcinoma, pancreatic cancer, and small cell lung cancer." (PMID 30625226, 2019). "This remodelling of endoplasmic reticulum Ca2+ levels could be therapeutically exploited, as demonstrated in small cell lung cancer cell lines, where a peptide inhibitor of the BCL-2-IP3R interaction enhances the apoptotic effect of navitoclax (ABT-263), a BCL-2/BCL-xL inhibitor." (PMID 39353922, 2024). "The potent effects observed on BCL2 and MYCN expression in our study highlight the potential therapeutic value of BET inhibitors in other solid tumors driven by high expression of these oncogenes, including small cell lung cancer, medulloblastoma, retinoblastoma, and rhabdomyosarcoma." (PMID 24009722, 2013).
non-Hodgkin lymphoma (73 papers, 1994 to 2025). Distinct from Hodgkin lymphoma both morphologically and biologically, non-Hodgkin lymphoma (NHL) is characterized by the absence of Reed-Sternberg cells, can occur at any age, and usually presents as a localized or generalized lymphadenopathy associated with fever and weight loss. "The tumorigenic potential of aberrant Bcl-2 protein expression was first associated with poor outcomes in non-Hodgkin’s lymphoma, and Bcl-2 overexpression was further identified in various solid tumors." (PMID 35053443, 2022). "The tumorigenic effect of Bcl-2 was first described in subsets of non-Hodgkin’s lymphoma (NHL), such as AML, where it has been found to be associated with chemoresistance and unfavorable outcomes." (PMID 32455818, 2020). "The disruption of the anti-apoptotic B-cell lymphoma 2 (BCL2) molecule is a hallmark of the majority of non-Hodgkin lymphomas." (PMID 32197371, 2020). "Chromosomal translocation as a mechanism of Bcl-2 gene activation is associated with non-Hodgkin’s lymphomas, while the loss of endogenous miRNA and gene hypomethylation were reported in chronic lymphocytic leukemia (CLL)." (PMID 30781512, 2019). "Indeed, oblimersen is well tolerated and causes a reduction in BCL2 protein levels after intravenous injection in patients with non-Hodgkin lymphoma." (PMID 39594617, 2024). "Current therapy for BCL-2-associated tumors such as Non-Hodgkin Lymphomas (NHL) is inadequate." (PMID 27283896, 2016). "PTEN presence, BCL2 mutations, and low or undetectable baseline IL-2 levels were associated with improved patient survival following treatment with C + R, supporting a potential role for these biomarkers in guiding treatment selection for patients with indolent non-Hodgkin lymphoma." (PMID 39984775, 2025). "In Hodgkin lymphoma, the expression of CD30 and PD-1 has enabled successful immune checkpoint blockade, whereas in non-Hodgkin lymphoma, the mutations of CD20 and BCL2 inform antibody-based and BCL2 inhibitor therapies." (PMID 41008611, 2025). "The mitochondrial pathway contributes to the development of non-Hodgkin’s lymphoma, and rituximab has been demonstrated to alleviate the chemotherapy resistance observed in individuals with BCL-2 overexpression." (PMID 39395994, 2024). "BCL2 is activated in hematological malignancies, such as chronic lymphocytic leukemias, multiple myelomas, and non-Hodgkin lymphomas." (PMID 39594617, 2024). "Anti-apoptotic Bcl-2, the founding member of this family, was discovered due to its dysregulated expression in non-Hodgkin’s lymphoma." (PMID 35056993, 2022). "Navitoclax binds to BCL-2, BCL-xL, and BCL-w in vitro, while BCL-2 plays a key role in vivo and high expression of BCL-2 exhibited sensitivity to Navitoclax in human non-Hodgkin lymphomas instead of BCL-xL or BCL-w." (PMID 34603598, 2021). "Our results align with previous work showing that normal lymphoid cell and human non-Hodgkin lymphoma resistance to ABT-737 is conferred by mutant BIM specific for BCL-2, BCL-XL, and BCL-W." (PMID 31692812, 2019). "Screening of two BCL2 transgenic models confirmed known drivers of human non-Hodgkin lymphoma, and implicates novel candidates including modifiers of immunosurveillance and MHC loci." (PMID 29985390, 2018). "The bcl-2 inhibitor, Venetoclax, as a single agent in non-Hodgkin Lymphoma has shown quite variable activity." (PMID 29765528, 2018). "The ratio of Bcl-2 and Bax protein expression was analyzed and correlated with the histological subtype of non-Hodgkin’s lymphomas." (PMID 29531548, 2017). "BCL2 is an oncogene, which was first identified in Non-Hodgkin lymphoma B-cells and this gene is a pivotal molecule in the mitochondrial apoptosis pathway." (PMID 22300941, 2012). "The anti-apoptotic factor Bcl2 is over-expressed in various non-Hodgkin lymphomas in which it prevents cell death induced by numerous apoptotic inducers targeting the mitochondria." (PMID 19430526, 2009).